CLDN23 (claudin 23)
Description:
Plays a major role in tight junction-specific obliteration of the intercellular space, through calcium-independent cell-adhesion activity.
Synonyms: CLDNL; hCG1646163
Tractability: Antibody: UniProt places it where antibodies can reach, with medium confidence; UniProt predicts a signal peptide or a membrane-spanning region; its Gene Ontology location is reachable by antibodies, with medium confidence; the Human Protein Atlas places it where antibodies can reach.
Gene: Protein-coding gene on chromosome 8 (8,701,937 to 8,704,096, forward strand). Ensembl gene ENSG00000253958.
Subcellular location: Cell junction, tight junction; Cell membrane
Subcellular location (Human Protein Atlas): Vesicles; Cell Junctions; Plasma membrane
Pathways (Reactome):
Cell-Cell communication: Tight junction interactions
Gene Ontology:
Molecular function: protein binding; identical protein binding; structural molecule activity
Biological process: calcium-independent cell-cell adhesion
Cellular component: bicellular tight junction; plasma membrane; membrane
Genetic constraint (gnomAD): Loss-of-function variants: 7 observed, 3.52 expected, observed/expected ratio (o/e) 1.99. That is too few expected variants to judge how well the gene tolerates losing a copy. Missense variants: 597 observed, 365.82 expected, observed/expected ratio (o/e) 1.63, 90% interval 1.52 to 1.75. Synonymous variants: 291 observed, 178.64 expected, observed/expected ratio (o/e) 1.63, 90% interval 1.48 to 1.79.
Homologues: Orthologues: chimpanzee CLDN23 (98% identical), macaque CLDN23 (89% identical), mouse Cldn23 (80% identical), rabbit CLDN23 (80% identical), rat Cldn23 (80% identical), pig CLDN23 (77% identical), tropical clawed frog cldn23 (45% identical), zebrafish cldn23.2 (31% identical), zebrafish cldn23.1 (30% identical). Paralogues in human: CLDN9 (21% identical), CLDN17 (20% identical), CLDN3 (20% identical), CLDN6 (20% identical), CLDN4 (19% identical), CLDN1 (19% identical), CLDN14 (18% identical), CLDN19 (18% identical), CLDN2 (18% identical), CLDN7 (18% identical), CLDN25 (17% identical), CLDN5 (17% identical), and 10 more.
Diseases named in the same sentence as CLDN23 in open-access papers:
CLDN23 is named in the same sentence as 32 diseases in open-access papers, as found by Europe PMC text mining. Sharing a sentence is not in itself a finding about the gene and the disease. The quoted sentences say what the papers report.
gastric cancer (9 papers, 2015 to 2025). A primary or metastatic malignant neoplasm involving the stomach. "Nevertheless, our data suggest that claudin-23 expression may have potential prognostic value in gastric cancer, and the underlying mechanisms should be clarified by further studies." (PMID 28350854, 2017). "In particular, claudin-23 positive expression was associated with poor prognostic outcomes of gastric cancer patients and may therefore serve as an independent prognosticator of patient survival." (PMID 28350854, 2017). "As for analysis of clinicopathologic parameters of gastric cancer, logistic multiple regression indicated that claudin-11 was significantly associated with sex, smoking, alcohol, H. pylori infection and Borrmann classification while claudin-23 was significantly associated with vessel cancer embolus." (PMID 28350854, 2017). "For example, CLDN23 gene is mapped to human chromosome 8p23.1 and played tumor suppressor effect in gastric cancer." (PMID 40528239, 2025). "Claudin-23 (CLDN23), which has been shown to be downregulated in gastric cancer, has also been implicated in CRC." (PMID 38540693, 2024). "Contrarily, positive claudin-23 expression is predictive of better overall survival in gastric cancer patients." (PMID 37627123, 2023). "In summary, downregulation of claudin-11, -23 in gastric cancer correlated with some clinicopathologic features; in particular, claudin-23 showed potential for development as a prognosticator of patient survival." (PMID 28350854, 2017). "Recently a study confirmed CLDN23 as a potential biomarker for the diagnosis and prognosis of gastric cancer, and it was further demonstrated that CLDN23 expression was positively correlated with GSTP1 activity in gastric cancer." (PMID 29116019, 2017). "The expression of claudin-23 in superficial gastritis was higher than that in atrophic gastritis and gastric cancer (P = 1.04*10−21), but was lower in atrophic gastritis than that in gastric cancer (P = 2.98*10−5)." (PMID 28350854, 2017). "For claudin-23, higher expression was observed in superficial gastritis than that in atrophic gastritis (P = 3.64*10−12) and gastric cancer (P = 9.06*10−14)." (PMID 28350854, 2017). "Decreased mRNA expression of claudin-23 has been observed in intestinal type of gastric cancer, but its protein expression level in gastric cancer is unclear." (PMID 28350854, 2017). "The expression of claudin-23 was also lower in gastric cancer than that in superficial gastritis at both the mRNA and protein level, which further confirmed previous reports of downregulation of claudin-23 mRNA in intestinal gastric cancer." (PMID 28350854, 2017). "Additionally, downregulation of the CLDN23 gene in gastric cancer has also been reported." (PMID 25574196, 2015). "Cox multivariate survival analysis indicated that gastric cancer patients with negative claudin-23 expression had significantly longer overall survival." (PMID 28350854, 2017). "The expression of claudin-23 was significantly lower in atrophic gastritis than that in gastric cancer, but no obviously difference was observed for claudin-11." (PMID 28350854, 2017).
colorectal cancer (6 papers, 2019 to 2024). A primary or metastatic malignant neoplasm that affects the colon or rectum. "Previously, a study had reported that CLDN23 is downregulated in tumors of colorectal cancer and the downregulated level is correlated with the prognosis of colorectal cancer patients." (PMID 31612869, 2019). "Our findings revealed that the mRNA expression levels of CLDN1, CLDN2, CLDN12, and CLDN14 were upregulated in colorectal cancer tissues relative to normal tissues in the Oncomine database, whereas CLDN3, CLDN5, CLDN7, CLDN8, CLDN11, CLDN15, and CLDN23 were downregulated, as previously reported." (PMID 35281827, 2022). "In addition, three genes were shown to be related with advanced colorectal cancer: CLDN11 (p = 0.007), and CLDN14 (p = 0.03) and CLDN23 (p = 0.021)." (PMID 35281827, 2022). "However, when comparing colorectal cancer tissues from the GEPIA database to normal colonic mucosa, the mRNA level expression of CLDN3, CLDN7, and CLDN23 was shown to be significantly higher in these tumor tissues." (PMID 35281827, 2022).
pancreatic cancer (3 papers, 2015 to 2024). "Studies on claudin-23 regulation in pancreatic cancer are scarce, and research on claudin-23 in pancreatic cancer could contribute to new targets for molecular therapy to prevent invasion and metastasis of pancreatic cancer." (PMID 36959784, 2023). "Moreover, claudin-23 expression is possibly correlated with the activation of the MEK signalling pathway during pancreatic cancer cell dissociation." (PMID 26083392, 2015).
colon cancer (2 papers, 2022 to 2023). "The risk score models identify that the CLDN23 is correlated to the disease prognosis in colon cancer patients." (PMID 37799140, 2023). "Then, we found that the expression of three deregulated claudins (CLDN11, CLDN14, and CLDN23) is significantly correlated with the shorter survival time of colon cancer patients as well as in the metadata of GSEA datasets." (PMID 37799140, 2023). "Our analysis revealed that the higher expression group of CLDN14 and CLDN11 are significantly correlated with the survival prognosis of colon cancer patients and the low expression group of CLDN23 is significantly correlated with shorter survival time of colon cancer patients." (PMID 37799140, 2023).
colorectal tumors (2 papers, 2020 to 2023). "It was demonstrated that the aberrant expression of CLDN2, CLDN4, CLDN5, CLDN7, and CLDN23 are associated with the clinical value in colorectal tumors." (PMID 37799140, 2023). "Expression of claudin-23 has been shown to be downregulated in tumour tissue and downregulation is associated with shorter overall survival in patients with colorectal tumours." (PMID 32408894, 2020).
colonic carcinoma (1 paper, 2017). "For instance, claudin-11 expression was higher in normal cholecyst tissues than that in cholecyst carcinoma tissues, whereas claudin-23 expression was downregulated in colonic carcinoma." (PMID 28350854, 2017).
deafness (1 paper, 2007). An inherited or acquired condition characterized by the complete loss of the ability to hear from one or both ears. "Although none of the variants segregated with the deafness phenotype in the analysed families, to completely rule out the involvement of CLDN23 gene as a modifying factor for A1555G mutation, a family based association test was performed." (PMID 18154640, 2007). "None of the identified SNPs in either CLDN23 or MRPS18CP2 segregate with the phenotype in A1555G families, but as modifying factors are likely to be multiple, this observation did not provide enough evidence to completely discard their contribution in the A1555G deafness phenotype." (PMID 18154640, 2007).
endometriosis (1 paper, 2025). The growth of functional endometrial tissue in anatomic sites outside the uterine body. "Although the vagina is an uncommon site for endometriosis, genes such as CLDN23, MFHAS1, and PRAG1 showed notable functional associations." (PMID 40863222, 2025). "From the Cancer Hallmarks perspective, GATA4, C2, MICB, and CLDN23 were implicated in evading immune destruction and tissue invasion, suggesting that even within intestinal tissues, relevant molecular signals associated with the pathophysiology of endometriosis may be present." (PMID 40863222, 2025). "In the ovary, (a tissue commonly affected by endometriosis) the prominent involvement of MFHAS1, CLDN23, USP4, and GATA4 was identified, all of which are regulated by eQTLs." (PMID 40863222, 2025).
invasive ductal breast carcinoma (1 paper, 2021). The most common type of invasive breast carcinoma, accounting for approximately 70% of breast carcinomas. "In the BC dataset of Turashvili’s study, CLDN18 was downregulated in invasive ductal breast carcinoma with a fold change of –2.301 (p = 1.89E-04) and CLDN23 was downregulated in invasive lobular breast carcinoma with a fold change of –3.776 (p = 0.025)." (PMID 33714203, 2021).
psoriasis (1 paper, 2011). An autoimmune condition characterized by red, well-delineated plaques with silvery scales that are usually on the extensor surfaces and scalp. "In all five mouse phenotypes, there was increased expression of S100a9, Lcn2, S100a8, Sprr1b, Mpzl2, Has3, as well as decreased expression of Tppp, Stxbp6, and Cldn23, and each of these effects is consistent with characteristic expression patterns in clinical psoriasis." (PMID 21483750, 2011).
rosacea (1 paper, 2025). A chronic erythematous skin disorder that affects the face. "Compared with healthy controls, KRT6A and KRT16 mRNA levels were significantly upregulated in rosacea, whereas CLDN1, CLDN16, OCLN, and KRT17 showed no significant changes, and CLDN23 was significantly downregulated." (PMID 40346694, 2025).
tumor (8 papers, 2007 to 2025). "Previous studies exploring the effects of CLDN1, CLDN2, CLDN4, CLDN11, CLDN12, CLDN14, and CLDN23 expression on CRC tumor growth have yielded findings consistent with our results in the present study." (PMID 35281827, 2022). "In parallel, based on the Cancer Hallmarks Gene Set, these same genes were associated with processes such as evading immune destruction, tumor-promoting inflammation, sustained angiogenesis, and tissue invasion and metastasis, particularly through the actions of CLDN23 and GATA4." (PMID 40863222, 2025). "CLDN23 showed low expression in tumor patient samples in GEO and TCGA databases." (PMID 35945754, 2022). "We found that between normal and tumor samples, CLDN8 and CLDN23 were downregulated and CLDN1 and CLDN2 were upregulated, respectively." (PMID 37799140, 2023). "All these molecules are known to be involved in cancer process, some being identified as tumour suppressor genes (e.g. GPR54 and CLDN23) and others related to angiogenesis (e.g. CXL1 and EDNRA) or cell migration capacities (e.g. PLAU)." (PMID 17406368, 2007). "Genes such as GATA4, CLDN23, MICB, MFHAS1, and BMPR2 were enriched in multiple signatures including estrogen response, coagulation, DNA repair, tumor-promoting inflammation, immune evasion, angiogenesis, sustained proliferative signaling, resistance to cell death, and metastasis." (PMID 40863222, 2025). "Known tumour suppressor genes, although not included in this list, were noted as downregulated in the array analysis for example, the FHIT (LBFC=−5.39) at 3p14.2; ST7 (LBFC=−2.95) at 7q31 or CLDN23 (LBFC=−4.58) at 8p23.1." (PMID 17406368, 2007).
cancer (7 papers, 2007 to 2025). A tumor composed of atypical neoplastic, often pleomorphic cells that invade other tissues. "CLDN23 encodes a claudin family member, and claudins are known to play a crucial role in cancer growth and progression." (PMID 38054820, 2023). "From the Cancer Hallmarks perspective, genes such as BMPR2, MICB, CLDN23, and WNT4 were linked to critical processes such as Replicative immortality, resistance to cell death, evading immune destruction, and angiogenesis." (PMID 40863222, 2025). "The result was consistent between WB and IHC in cancer tissues for claudin-23 expression (kappa = 0.854, P = 1.12*10−10) and marginally consistent for claudin-11 expression (kappa = 0.203, P = 0.011)." (PMID 28350854, 2017). "This chromosomic region harbours the CSMD1, AGPAT5, TUSC3, DLC1, CLDN23, and MFHAS1 cancer-related genes." (PMID 30185896, 2018).
CLDN23 also shares sentences with these, for which no sentence is quoted: adenoma (1 paper); atopic dermatitis (1); atrophic gastritis (1); breast carcinoma (1); colitis (1); colon adenocarcinoma (1); congenital heart malformation (1); coronary artery disease (1); heart disease (1); hepatocellular carcinoma (1); Hypertension (1); hypoplastic left heart syndrome (1); infection (1); intestinal tumors (1); invasive lobular breast carcinoma (1); metastasis (1); non-small cell lung carcinoma (1); Sepsis (1); ventricular septal defect (1).